RRAGC (Ras related GTP binding C)
Description:
Guanine nucleotide-binding protein that plays a crucial role in the cellular response to amino acid availability through regulation of the mTORC1 signaling cascade. Forms heterodimeric Rag complexes with RagA/RRAGA or RagB/RRAGB and cycles between an inactive GTP-bound and an active GDP-bound form: RagC/RRAGC is in its active form when GDP-bound RagC/RRAGC forms a complex with GTP-bound RagA/RRAGA (or RagB/RRAGB) and in an inactive form when GTP-bound RagC/RRAGC heterodimerizes with GDP-bound RagA/RRAGA (or RagB/RRAGB). In its GDP-bound active form, promotes the recruitment of mTORC1 to the lysosomes and its subsequent activation by the GTPase RHEB. This is a crucial step in the activation of the MTOR signaling cascade by amino acids. Also plays a central role in the non-canonical mTORC1 complex, which acts independently of RHEB and specifically mediates phosphorylation of MiT/TFE factors TFEB and TFE3: GDP-bound RagC/RRAGC mediates recruitment of MiT/TFE factors TFEB and TFE3.
Synonyms: RagC; GTR2; FLJ13311; LNGODS; LNGOS; TIB929
Tractability: Small molecule: a structure with a bound ligand is known. PROTAC: ubiquitination databases record sites on it; its protein half-life has been measured.
Gene: Protein-coding gene on chromosome 1 (38,838,198 to 38,859,772, reverse strand). Ensembl gene ENSG00000116954.
Subcellular location: Cytoplasm; Nucleus; Lysosome membrane
Subcellular location (Human Protein Atlas): Nucleoplasm; Vesicles
Pathways (Reactome):
Signal Transduction: Energy dependent regulation of mTOR by LKB1-AMPK; MTOR signalling; Regulation of PTEN gene transcription; mTORC1-mediated signalling
Autophagy: Macroautophagy
Cellular responses to stimuli: Amino acids regulate mTORC1
Gene Ontology:
Molecular function: enzyme-substrate adaptor activity; GDP binding; GTP binding; GTPase activity; GTPase binding; molecular adaptor activity; protein binding; protein heterodimerization activity; protein-membrane adaptor activity; magnesium ion binding
Biological process: cellular response to amino acid starvation; cellular response to nutrient levels; positive regulation of TORC1 signaling; protein localization to lysosome; protein localization to membrane; regulation of TOR signaling; regulation of TORC1 signaling; response to amino acid; apoptotic process; cellular response to amino acid stimulus; cellular response to starvation; DNA-templated transcription; intracellular protein localization; negative regulation of autophagy; RNA splicing; small GTPase-mediated signal transduction
Cellular component: cytoplasm; FNIP-folliculin RagC/D GAP; Gtr1-Gtr2 GTPase complex; lysosomal membrane; lysosome; nucleoplasm; nucleus; cytosol
Genetic constraint (gnomAD): Loss-of-function variants: 6 observed, 21.71 expected, observed/expected ratio (o/e) 0.28, 90% interval 0.15 to 0.55. The upper end of that interval is the gene's LOEUF score, 0.55, which puts it in group 2 of 6, group 1 being the genes least tolerant of losing a copy. Missense variants: 285 observed, 384.34 expected, observed/expected ratio (o/e) 0.74, 90% interval 0.67 to 0.82. Synonymous variants: 155 observed, 142.53 expected, observed/expected ratio (o/e) 1.09, 90% interval 0.95 to 1.24.
Homologues: Orthologues: chimpanzee RRAGC (100% identical), macaque RRAGC (100% identical), dog RRAGC (99% identical), guinea pig RRAGC (99% identical), pig RRAGC (99% identical), mouse Rragc (99% identical), rabbit RRAGC (89% identical), rat Rragc (85% identical), zebrafish rragca (84% identical), zebrafish rragcb (81% identical), tropical clawed frog rragc (78% identical), zebrafish rragd (72% identical), and 2 more. Paralogues in human: RRAGD (77% identical), RRAGB (23% identical), RRAGA (21% identical).
Diseases named in the same sentence as RRAGC in open-access papers:
RRAGC is named in the same sentence as 32 diseases in open-access papers, as found by Europe PMC text mining. Sharing a sentence is not in itself a finding about the gene and the disease. The quoted sentences say what the papers report.
follicular lymphoma (7 papers, 2021 to 2025). Follicular lymphoma is a form of non-Hodgkin lymphoma characterized by a proliferation of B cells whose nodular structure of follicular architecture is preserved. "One prominent exception is the case of follicular lymphoma in which RRAGC gene mutations occur somatically and, therefore, the disease is not inherited." (PMID 38987251, 2024). "Of these, mutations in CREBBP, KMT2D, TNFRSF14 and RRAGC were enriched in follicular lymphoma, and those of BTG2, HLA-A, PIM1, IGLL5, SOCS1, CD83 and SGK1 were enriched in DLBCL." (PMID 33945543, 2021). "WES previously revealed recurrent mTORC1‐activating mutations in RRAGC, which encodes RagC, in follicular lymphoma; the mutants increased raptor binding while rendering mTORC1 signaling resistant to amino acid deprivation." (PMID 33107222, 2021). "Studies have shown that RRAGC-activating mutations are found in approximately 10% of follicular lymphomas, with the mutated RRAGC protein showing increased binding to RPTOR (raptor) and significantly reduced interaction with the product of the tumor suppressor gene FLCN (follicle protein)." (PMID 40414942, 2025). "As expected, mutations in frequent drivers such as CREBBP, KMT2D,TNFRSF14 and RRAGC were more frequent among follicular lymphomas, those of MYC, CCND3 and ID3 prevailed among Burkitt lymphoma and those of BTG2, PIM1, SGK1 and SOCS1 were more frequent among DLBCL." (PMID 33945543, 2021).
dilated cardiomyopathy (4 papers, 2021 to 2024). Cardiomyopathy which is characterized by dilation and contractile dysfunction of the left and right ventricles. "More recently, an extensive study based on genomic sequencing in children with dilated cardiomyopathy identified several germline mutations in the RRAGC gene affecting amino acids Ser75, Thr90, Tyr115, and Pro118, which are located within the nucleotide-binding domain." (PMID 38987251, 2024). "Therefore, mTOR inhibition failed to restore nuclear translocation of TFEB or ameliorate cardiomyopathy in RRAGC-mutant-related dilated cardiomyopathy." (PMID 37749558, 2023).
lymphoma (2 papers, 2023 to 2024). A malignant (clonal) proliferation of B- lymphocytes or T- lymphocytes which involves the lymph nodes, bone marrow and/or extranodal sites. "The cardamonin-induced decrease in Raptor expression further disrupted the formation of the mTOR-activating complex and led to a more efficient inhibition of RRAGC-mutant lymphomas." (PMID 37749558, 2023). "Since cardamonin exerted an inhibitory effect on mTOR, we speculated that RRAGC-mutant lymphoma cells were selectively sensitive to cardamonin." (PMID 37749558, 2023).
melanoma (2 papers, 2025). A malignant, usually aggressive tumor composed of atypical, neoplastic melanocytes. "The expression of RRAGD together with partner RRAGC were checked in melanoma tumors and cells." (PMID 40651979, 2025).
prostate carcinoma (2 papers, 2017 to 2020). A carcinoma that arises from epithelial cells of the prostate gland. "In prostate cancer, genetic alterations in RRAGA and RRAGC genes that encode RAGA and RAGC respectively are uncommon, however RRAGB (encoding RAGB) is amplified in up to 7.7% of cases and RRAGD (encoding RAGD) deep deletion occurs in 6.5–14.4% of cases." (PMID 32630372, 2020).
B-cell lymphoma (1 paper, 2023). "Hence, oncogenic RRAGC mutation strongly enhances mTOR activation and accelerates B cell lymphoma cell proliferation." (PMID 37749558, 2023). "Second, in the Raptor shRNA experiment, we concluded that Raptor partially mediated the inhibitory effect of cardamonin on RRAGC-mutant B-cell lymphoma." (PMID 37749558, 2023). "In this study, we evaluated the inhibitory effects of cardamonin on RRAGC-mutant B-cell lymphoma." (PMID 37749558, 2023).
breast carcinoma (1 paper, 2018). "Furthermore, high CAP1 expression was associated with poor tumor characteristics and correlated with expression of genes and biological pathways within growth promoting (such as Abl, RRAGC and mTOR) and cell motility processes (e.g., Arp2/3 complex, ARSB and FN1) in breast cancer." (PMID 30524378, 2018).
tumor (12 papers, 2018 to 2026). "Mouse xenografts implanted with SUDHL-4 cells expressing mutant RRAGC exhibited a significantly higher tumour growth rate than those expressing WT RRAGC." (PMID 37749558, 2023). "Furthermore, the phosphorylation of mTOR signalling and cell viability increased in RRAGC-mutant cells, as well as the tumour growth rate of RRAGC-mutant-harbouring animals." (PMID 37749558, 2023). "Furthermore, our validation results suggested that the loss of four mTOR-related genes (PTEN, FLCN, RRAGC, and RPS6KA1) was associated with enhanced long-term proliferation and target tumor cell killing." (PMID 35990699, 2022). "However, the gene‐level integrated analysis revealed heterogeneity in expression, copy number variation and methylation status of MDM4, RRAGC, HERC2, BIRC3 and TSC2 genes within and across individual tumours, suggesting that they may not be ideal biomarkers for PDAC." (PMID 35061935, 2022).
cancer (8 papers, 2022 to 2025). A tumor composed of atypical neoplastic, often pleomorphic cells that invade other tissues. "The translocation of MTORC1 from cytosol to lysosome surface by RRAGC GTase is a key step in MTORC1 activation, and inhibition of RRAGC expression can also inhibit the growth of cancer cells." (PMID 40414942, 2025). "Hence, RRAGC regulates cancer occurrence and may be a key gene in the modulation of OSCC." (PMID 40414942, 2025). "In the Cancer Cell Line Encyclopedia (CCLE), expression of FNIP2 and RRAGD, and to some extent RRAGC, but not RRAGA or RRAGB, correlates with MITF expression." (PMID 41275493, 2025).
RRAGC also shares sentences with these, for which no sentence is quoted: cardiomyopathy (3 papers); colorectal cancer (2); hepatoma (2); liver cancer (2); PEComas (2); adrenocortical carcinoma (1); astrocytomas (1); benign skin tumors (1); Burkitt lymphoma (1); diffuse large B-cell lymphoma (1); focal epilepsies (1); glioma (1); infection (1); leukemia (1); malignant glioma (1); mesothelioma (1); nonalcoholic fatty liver disease (1); Obesity (1); ovarian carcinoma (1); pancreatic adenocarcinoma (1); progeria (1); renal carcinoma (1); tuberous sclerosis (1).